CTNNB1 (catenin beta 1)
Diseases named in the same sentence as CTNNB1 in open-access papers (continued):
Sharing a sentence is not in itself a finding about the gene and the disease.
hepatoblastoma (57 papers, 2011 to 2026). Hepatoblastoma (HB) is a malignant hepatic tumor and is the most common pediatric liver cancer. "Mouse models of hepatoblastoma have demonstrated that CTNNB1 point mutations, in combination with the YAP1 oncogene, result in a more differentiated tumor phenotype than that of CTNNB1 exon 3–deletion mutant." (PMID 40684183, 2025). "Genetic mouse models have shown that CTNNB1 mutations alone are insufficient to initiate hepatoblastoma." (PMID 40684183, 2025). "The sialoblastoma from Patient 5 did not have an FGFR2 variant and instead showed a CTNNB1 missense hotspot variant (CTNNB1 p.I35T); the concurrent hepatoblastoma in this patient had a distinct CTNNB1 hotspot variant (CTNNB1 p.S45P)." (PMID 40906279, 2025). "Genomic studies have revealed a remarkably low tumor mutational burden, with up to 80–90% of hepatoblastomas containing mutations of the CTNNB1 gene that abrogate degradation of the β-catenin protein, leading to constitutive activation of the Wnt pathway." (PMID 39567523, 2024). "Within the realm of genomics, gene mutations, particularly those occurring in the CTNNB1 gene, have been identified as the primary drivers of hepatoblastoma." (PMID 38390281, 2024). "WNT-activating mutations in CTNNB1 are common in hepatoblastoma, but downstream molecular phenotypes are heterogenous." (PMID 39567475, 2024). "The majority of hepatoblastoma cases (> 90%) carry a mutation in the CTNNB1 gene encoding for β-catenin." (PMID 39567475, 2024). "Mutations in the CTNNB1 gene, which encodes β-catenin, are present in approximately 70–80% of hepatoblastoma cases and result in aberrant activation of the Wnt signaling pathway, leading to uncontrolled cell proliferation and tumor development." (PMID 39596558, 2024). "QUENCH was designed to capture variants in exon 3 of the CTNNB1 gene, as it is a hallmark of sporadic hepatoblastoma, with single mutation genotyping confining ctDNA detection limits to 0.1% VAF." (PMID 38201440, 2023). "Hepatoblastoma is characterized by driver mutations in CTNNB1, making it an attractive biomarker for a liquid biopsy approach utilizing circulating tumor DNA (ctDNA)." (PMID 38201440, 2023). "Mutation of CTNNB1 occurs in about 48–67% of pediatric hepatoblastoma cases, which is different from how liver tumors arise in our model." (PMID 37414763, 2023). "While hepatoblastoma typically has a low mutational burden, a frequent recurrent alteration is the mutation or deletion of exon 3 of the CTNNB1 gene." (PMID 38201440, 2023). "Driver mutations in CTNNB1 are a hallmark of hepatoblastoma and offer a common biomarker for a liquid biopsy approach that is based on the presence of CTNNB1 circulating tumor DNA (ctDNA)." (PMID 38201440, 2023). "The exception was CTNNB1, which was mutated in 7 of 11 (64%) hepatoblastomas with exome sequencing data." (PMID 37990009, 2023). "The majority of work has centered around identifying and characterizing molecular drivers and subtypes, such as CTNNB1-mutated hepatoblastoma, or that occurring in patients with germline antigen-presenting cell mutations." (PMID 37426669, 2023). "Mutations in the Catenin Beta 1 (CTNNB1) exon 3 region were detected in 54 of 59 samples (92%) of pediatric hepatoblastoma; In such tumors, Wnt signaling and cell cycle pathways are usually upregulated." (PMID 36249028, 2022). "Similar to desmoid tumors and hepatoblastoma, somatic CTNNB1 mutations are common in sporadic hepatoblastoma (50–90% of patients) and likely mutually exclusive with germline APC mutations, although further research is needed." (PMID 35158896, 2022). "In hepatoblastoma, CTNNB1 mutations have been found in up to 67% of cases, all affecting exon 3 which encodes the degradation targeting box of β-catenin, resulting in nuclear β-catenin accumulation." (PMID 34725446, 2022). "Hepatoblastomas (HB), the most common malignant liver tumors in children, carry up to 90% deletions and/or missense mutations in the CTNNB1 gene." (PMID 34235580, 2021).
hepatoblastoma (continued). "Hepatoblastoma generally presents with a large abdominal mass, activating mutations of the catenin beta 1 (CTNNB1) gene, and an elevated α-fetoprotein protein (AFP) level." (PMID 33790968, 2021). "As the most common pediatric liver malignancy, hepatoblastoma is believed to be a Wnt–β-catenin-activated malignant tumor, with frequent mutations in the catenin beta 1 (CTNNB1) gene that encodes β-catenin." (PMID 34926299, 2021). "HepG2, derived from an hepatoblastoma, displays 299 mutations and CNAs including CTNNB1 exon 3 deletion and NRAS missense mutation." (PMID 32515546, 2020). "Nevertheless, the mutations in CTNNB1 genes (β-catenin) are most frequently observed in hepatoblastoma patients and an increase in cytoplasmic and nuclear immunostaining of β-catenin has been documented in these cases of hepatoblastoma." (PMID 31511432, 2019). "Mutations in CTNNB1 which encodes for beta-catenin protein have also been recognized as a marker of poor prognosis in hepatoblastoma." (PMID 30969990, 2019). "Regarding hepatoblastoma biology, it is reported that CTNNB1 mutations and the Wnt pathway, which regulates this gene, are involved in the initiation of this cancer." (PMID 30373285, 2018). "As for somatic alterations, we detected a CTNNB1 hotspot mutation and chromosome 1q gain, both of which were well-known somatic alterations in hepatoblastoma, suggesting a pivotal role for development of the hepatoblastoma." (PMID 29190888, 2017). "Recent whole-exome sequencing studies showed a high prevalence of β-catenin(CTNNB1) gene mutations in hepatoblastoma tumor specimens." (PMID 28851352, 2017). "The CTNNB1 p.G34V has been reported as a recurrent driver mutation occurring in hepatoblastoma and in other human cancers." (PMID 29190888, 2017). "Functional enrichment analysis of the genes affected by abnormal methylation have highlighted the Wnt signaling pathway, typically altered in hepatoblastomas mainly through a high frequency of CTNNB1 activating mutations." (PMID 29228658, 2017). "Histologic type and subtype, β-catenin and Y654 β-catenin IHC and CTNNB1 gene status of hepatoblastomas with mutations." (PMID 21992464, 2011). "And although β-catenin gene mutations have been widely reported in hepatoblastoma, a disparity exists between the reported frequency of aberrant β-catenin protein accumulation and mutations in the CTNNB1 gene." (PMID 21992464, 2011). "Here we report an analysis of the role of HGF/c-Met related β-catenin activation and CTNNB1 mutation activation of β-catenin in a large cohort of 84 patients with hepatoblastoma." (PMID 21992464, 2011). "To identify CTNNB1 mutations we extracted total RNA from corresponding tissue cores of hepatoblastoma." (PMID 21992464, 2011). "Finally, mutations in CTNNB1, which encodes β-catenin and is found in 70–80% of hepatoblastoma cases, further drive metabolic reprogramming by increasing the expression of pyruvate dehydrogenase kinase 1 (PDK1)." (PMID 39596558, 2024). "Hepatoblastoma biopsies were examined for histology and CTNNB1 mutations." (PMID 34235580, 2021). "Somatic mutations in the exon 3 of β-catenin gene (CTNNB1) may lead to activation of Wnt/β-catenin signaling in hepatoblastoma, which is characterized by increased cytoplasmic/nuclear accumulation of β-catenin." (PMID 31511432, 2019). "With frequent CTNNB1 mutations, hepatoblastoma is a Wnt/β‐catenin‐driven malignancy." (PMID 28923827, 2017). "In contrast, IHC analysis of 20 hepatoblastoma with CTNNB1 mutations or possible deletions showed 5 (25%) were completely negative for Y654-β-catenin, 14 (70%) had cytoplasmic staining alone, and only one of 20 (5%) had nuclear expression in addition to cytoplasmic staining." (PMID 21992464, 2011). "Notably, this patient’s concomitant hepatoblastoma harbored a distinct CTNNB1 mutation (p.S45P)." (PMID 40906279, 2025).
hepatoblastoma (continued). "Up to 89% of hepatoblastoma tumors in Taiwan have been reported to contain mutations, including deletions and missense mutations, in exon 3 of the β-catenin (CTNNB1) gene, and 87% in a Western study were reported to carry mutations within the ubiquitination domain of the β-catenin (CTNNB1) gene." (PMID 28851352, 2017). "The high co-occurrence of CTNNB1 and 11p15.5 alterations in hepatoblastoma suggests that both genetic events are required for tumorigenesis." (PMID 40684183, 2025). "Conversely, in hepatoblastoma, WNT pathway dysregulation often arises from mutations in CTNNB1 as well as deletions or the epigenetic silencing of AXIN1 and AXIN2, which act as negative regulators of the pathway." (PMID 39851951, 2025). "The hepatoblastoma driver genes CTNNB1 and NFE2L2, along with liver-specific transcription factors HNF1A and HNF4A, were also found to be essential for cell survival." (PMID 40684183, 2025). "Although the 11p15.5 alterations in premalignant hepatocytes represent an early step in hepatoblastoma development, they can occur late or synchronously with CTNNB1 alterations." (PMID 40684183, 2025). "Like medulloblastoma, hepatoblastoma is also of embryonic origin, and tumor cells are frequently affected by genomic alterations in the CTNNB1 gene." (PMID 39851951, 2025). "Hepatoblastoma samples exhibited strong GLUL expression and glutamine synthesis, generally as a result of CTNNB1 mutations." (PMID 39684755, 2024). "Mutations in key genes of the WNT pathway, such as CTNNB1 and AXIN1, have been observed in BWS embryonal tumors, including hepatoblastoma, Wilms tumor, and pancreatoblastoma." (PMID 38612397, 2024). "Combination of the activated form of YAP1 (YAPS127A) with either hepatoblastoma relevant NFE2L2 mutant or CTNNB1 mutant promotes liver tumorigenesis although either alone is unable to transform normal liver cells in these mouse models." (PMID 37414763, 2023). "About half of hepatoblastomas exhibit large deletions within the CTNNB1 exon 3 locus (up to about 1000 bp), and the detection of ctDNA SVs, including deletions, necessitates innovative strategies given the fragmented nature of ctDNA." (PMID 38201440, 2023). "We provide promising evidence for the utility of quantitative CTNNB1 ctDNA detection in hepatoblastoma for dynamic tumor burden and treatment response monitoring, compared with the current clinical indicators and biomarkers for this disease." (PMID 38201440, 2023). "CTNNB1 (encoding β-catenin), APC and Axin mutations can be detected in up to 80% of cases of hepatoblastoma, indicating that the Wnt/β-catenin signaling pathway plays a vital role in the formation of hepatoblastoma." (PMID 35200654, 2022). "To mimic CTNNB1 active mutations in hepatoblastoma and HCC, we first generated albumin (Alb)-Cre–mediated hepatic Ctnnb1 exon 3–deleted mice." (PMID 36122209, 2022). "For example, METTL3-mediated m6A mRNA methylation promoted the proliferation of hepatoblastoma through the regulation of CTNNB1, while METTL3 promoted temozolomide resistance by increasing the expression of MGMT and ANPG." (PMID 35571106, 2022). "In hepatoblastoma, METTL3 promotes development of hepatoblastoma development through increasing the expression of CTNNB1 via regulation of the Wnt/β-catenin pathway." (PMID 32513173, 2020). "This study evidenced that CTNNB1 abnormalities collectively account for most of the genetic defects in hepatoblastoma and its increased levels are present in almost all hepatoblastoma cases." (PMID 30373285, 2018). "We transfected the parental HuH6 hepatoblastoma cell line with a doxycycline-inducible shRNA against CTNNB1 (gene coding for β-catenin) to obtain an isogenic cell line pair with or without aberrant β-catenin signaling." (PMID 26715116, 2015). "In 78 hepatoblastoma with wild type CTNNB1, 26 (33%) showed nuclear expression of Y654-β-catenin, 44 (56%) showed cytoplasmic staining with only 7 (9%) negative for staining." (PMID 21992464, 2011).
hepatoblastoma (continued). "Also, CTNNB1 is highly expressed in cancer tissues of children with hepatoblastoma (HB), which is closely related to the initial methotrexate, POST-TEXT staging, tumor diameter, and the presence of tumor invasion or metastasis." (PMID 40230723, 2025). "Early studies identified genetic mutations in CTNNB1, APC, AXIN1, AXIN2 in hepatoblastoma." (PMID 40684183, 2025). "Mutations in this region of CTNNB1 were identified in samples from HB3, HB5, HB7 and HB9 in our cohort, consistent with previous reports of such mutations being present in 60–90% of hepatoblastoma tumors." (PMID 32962010, 2020). "At somatic levels, previously known CTNNB1 mutation and chromosome 1q gain were identified driver events, but no additional driver events were uncovered in the hepatoblastoma." (PMID 29190888, 2017). "The development of hepatoblastoma in this BWS infant can be explained by predisposition of UPD at 11p15.5 as well as possibly of APC and PALB2 mutations and later by somatic events with CTNNB1 somatic mutation and 1q gain acting as driver alterations." (PMID 29190888, 2017). "In a previous WES of a hepatoblastoma with BWS, there was only a CTNNB1 mutation in the tumor." (PMID 29190888, 2017). "Hepatoblastoma occurring in patients with germline antigen-presenting cell mutations have lower grade tumors with higher frequency of fetal histology (a positive prognostic factor), absence of CTNNB1 mutations and better clinical outcomes." (PMID 37426669, 2023). "While direct activation of β-catenin by CTNNB1 mutation is common in many tumours, pathologic activation of β-catenin by HGF/c-Met signaling with associated transformation has also been reported in several tumors and its activation has been previously reported in hepatoblastoma." (PMID 21992464, 2011). "In hepatoblastoma (HB), METTL3/m6A methylation significantly affects the Wnt/β-catenin pathway by decreasing the expression and stability of CTNNB1, the coding gene of β-catenin." (PMID 40136363, 2025). "In hepatoblastoma cells, increased METTL3 activity resulted in increased m6A deposition on Ctnnb1, leading to aberrant activation of the WNT/CTNNB1 pathway, which promoted hepatoblastoma cell growth." (PMID 35350378, 2022). "Mechanistically, methylation of CTNNB1 transcripts by METTL3 increases the expression of β-catenin, which is involved in the regulation of tumor immunity, thereby increasing the proliferation and tumorigenicity of hepatoblastoma cells." (PMID 35254013, 2022).
ovarian carcinoma (50 papers, 2008 to 2025). A malignant neoplasm originating from the surface ovarian epithelium. "In ovarian cancer patients, CTNNB1 mutations are often associated with specific subtypes, such as ovarian clear cell carcinoma and endometrioid carcinoma." (PMID 38391958, 2024). "CTNNB1 (β-Catenin-1) mutations in ovarian cancer refer to genetic alterations in the CTNNB1 gene that encodes the beta-catenin protein." (PMID 38391958, 2024). "The results showed that CTNNB1 mutation existed in around 6% of ovarian cancer patients; among that the most common CTNNB1 gene alterations were copy number variation (CNV) gain and gene overexpression." (PMID 35646632, 2022). "Aberrant immunohistochemical expression of β-catenin (nuclear/cytoplasmatic) has also been demonstrated as a surrogate for β-catenin gene (CTNNB1) mutations in ovarian carcinoma." (PMID 35328186, 2022). "A CTNNB1 mutational analysis of 149 ovarian cancer samples detected 16% of endometrioid tumors harbored activating CTNNB1 mutations." (PMID 32560059, 2020). "Catenin (cadherin-associated protein) beta-1 (CTNNB1) mutations are quite peculiar to ovarian endometrioid carcinoma, at variance with other types of ovarian carcinoma." (PMID 29743986, 2018). "In ovarian cancer, somatic mutations in CTNNB1 (encoding β-catenin) are directly linked to carcinogenic transformation, but they are rare and mostly found in endometrioid adenocarcinomas." (PMID 19732438, 2009). "CTNNB1 mutations in the ovary are characteristic features of ovarian carcinomas." (PMID 37221474, 2023). "Furthermore, the CTNNB1 expression at the transcriptional level was negatively associated with the survival of ovarian cancer patients." (PMID 35646632, 2022). "CTNNB1 gene mutation in ovarian cancer mainly results in the gain of function of β-catenin." (PMID 35646632, 2022). "In ovarian cancer, Wnt/β-catenin signaling might be activated by increased expression of β-catenin and glycogen synthase kinase 3β (GSK3β), mutations of catenin beta 1 (CTNNB1) gene, and so on." (PMID 27708548, 2016). "Endometrioid ovarian carcinomas show broad morphological similarities to their endometrial counterparts with the most common molecular alterations in endometrioid OC including mutations in CTNNB1 (31–53.3%), PIK3CA (15–40%), ARID1A (30%), and PPP2R1A (7–16.6%)." (PMID 41153668, 2025). "Also, mutations in the CTNNB1 gene have been reported in some cancers, including ovarian cancer." (PMID 39309198, 2024). "Since CTNNB1 mutations are also common in ovarian endometrioid carcinoma (even more than in its endometrial counterpart), it cannot be excluded that CTNNB1 status might also be clinically useful in ovarian carcinoma." (PMID 35034160, 2022). "The other ovarian cancer subtypes show mutations in KRAS, BRAF, PTEN, and CTNNB1 (Beta-catenin), as well as a relatively stable karyotype." (PMID 35328186, 2022). "The most frequent genetic alteration in Wnt/β-catenin signaling in ovarian cancer is in the CTNNB1, the gene of β-catenin." (PMID 35646632, 2022). "Hyperactivity of β-catenin, in the case of ovarian cancer, and mutations of AXIN, CTNNB1, and APC genes were observed in epithelial ovarian cancer (EOC)." (PMID 34439332, 2021). "The Wnt/β-catenin pathway, established by CTNNB1 encoding β-catenin, was a crucial signaling pathway implicated in the epithelial-mesenchymal transition (EMT) and has been shown to play a significant role in the carcinogenesis of ovarian cancer." (PMID 40612060, 2025). "Besides, high frequency mutation of several pathway components have been observed in ovarian cancer, such as CTNNB1, AXIN1/2, and APC." (PMID 36185280, 2022).